Y_RNA (Y RNA )
Gene: Miscellaneous RNA gene on chromosome 17 (75,431,990 to 75,432,087, forward strand). Ensembl gene ENSG00000202332.
Homologues: Orthologues: chimpanzee Y_RNA (99% identical), macaque Y_RNA (96% identical), guinea pig Y_RNA (90% identical). Paralogues in human: RNY3 (92% identical), Y_RNA (91% identical), Y_RNA (90% identical), RNY3P1 (89% identical), Y_RNA (89% identical), Y_RNA (88% identical), RNY3P16 (87% identical), Y_RNA (87% identical), Y_RNA (86% identical), RNY3P14 (85% identical), RNY3P5 (85% identical), Y_RNA (85% identical), and 97 more.